TBK1 (TANK binding kinase 1)
Diseases named in the same sentence as TBK1 in open-access papers (continued):
Sharing a sentence is not in itself a finding about the gene and the disease.
breast tumors (1 paper, 2022). "On the other hand, TBK1 mRNA was significantly overexpressed in all breast tumors from NHW patients, and in NHW patients with basal, and Luminal A subtypes." (PMID 36494865, 2022). "NHW women with Her2 + breast tumors significantly overexpress TTK, TBK1, Nek2, BUB1, and SGOI." (PMID 36494865, 2022).
Burkitt lymphoma (1 paper, 2015). A rare form of malignant mature B-cell non-Hodgkin lymphoma. "Similar findings were manifest in U937 myeloid leukaemia cells and Daudi Burkitt lymphoma cells, and a second phospho-TBK1 antibody showed similar localization of pTBK1." (PMID 26656453, 2015).
colorectal tumor (1 paper, 2022). "We further compared the TBK1 expression by western blotting and IHC between colorectal tumor tissues and paracancer tissues." (PMID 35637944, 2022).
contact dermatitis (1 paper, 2023). An inflammatory skin condition caused by direct contact between the skin and either an irritating substance or an allergen. "Our current findings imply that intrathecal morphine injection, dry skin and contact dermatitis might inhibit spinal STING expression to reduce the phosphorylation of TBK1 and IRF3, causing acute and chronic itch." (PMID 37122031, 2023). "First, spinal expression of STING and spinal phosphorylation of TBK1 and IRF3 are decreased in mice with morphine injection, dry skin and contact dermatitis." (PMID 37122031, 2023). "Furthermore, DMXAA drastically increases spinal phosphorylation of TBK1 and IRF3 following morphine exposure, dry skin and contact dermatitis." (PMID 37122031, 2023).
cutaneous leishmaniasis (1 paper, 2022). Leishmaniasis affecting the skin. "Collectively, these results suggest that leishmania parasites might hijack the cGAS-STING-TBK1 signaling pathway to their own advantage and the TBK1 inhibitor amlexanox could be of interest as a candidate drug in treatment of cutaneous leishmaniasis." (PMID 36405710, 2022).
dermatitis (1 paper, 2023). An inflammatory process affecting the skin. "Second, STING agonism increases spinal STING-dependent phosphorylation of TBK1 and IRF3 in morphine-induced acute itch and dermatitis-induced chronic itch." (PMID 37122031, 2023).
Dyscalculia (1 paper, 2022). A specific learning disability involving mathematics and arithmetic. "Accordingly, 42.9% (3/7) of the TBK1 variant carriers had parietal damage associated symptom, such as dyscalculia, visuospatial dysfunction." (PMID 35964197, 2022).
Epstein-Barr virus infection (1 paper, 2017). An infection that is caused by Epstein-Barr virus. "Additionally, the pathway ‘Epstein-Barr virus infection’ was simultaneously enriched, in which several genes including BCL2, CD39, HSP70, HDAC45, IL10, IL10R and vimentin were up-regulated, together with some down-regulated genes such as CD38, NUP214, RBP-Jκ, CycA, TAK1 and TBK1." (PMID 28912500, 2017).
familial amyotrophic lateral sclerosis (1 paper, 2022). An instance of amyotrophic lateral sclerosis that is caused by an inherited modification of the individual's genome. "TBK1 mutations are associated with familial amyotrophic lateral sclerosis, and the STING pathway has been implicated in the pathogenesis of further neurodegenerative diseases." (PMID 36314770, 2022).
fungal infection (1 paper, 2018). "The formation of the InsP3R-SEC5 complex not only promoted InsP3R-mediated [Ca2+]c elevation, which is necessary for macrophage phagocytosis, but also enhanced TBK1 activity to activate the IRF-3-dependent type I interferon innate immune response against fungal infection." (PMID 29703257, 2018). "To determine if the SEC5-TBK1-IRF-3 signaling cascade is involved in C. albicans infection, we analyzed the phosphorylation of TBK1 (p-TBK1) and IRF-3 nuclear translocation during fungal infection, the results of which showed that C. albicans stimulation increased p-TBK1 levels in RAW264.7 cells." (PMID 29703257, 2018).
gastrointestinal carcinomas (1 paper, 2022). "Of clinical relevance, data from the villin+ intestinal epithelium-specific knockout of Tbk1 suggest that the use of TBK1 inhibitors would be contraindicated in at least some patients with gastrointestinal carcinomas." (PMID 35395857, 2022).
Giardia infection (1 paper, 2022). "Interestingly, Giardia infection up-regulates several downstream RIG-I signaling pathway genes during the infection, such as TRAF3, IKK, and TBK1." (PMID 35573800, 2022).
gingivitis (1 paper, 2019). A disorder involving inflammation of the gums; may affect surrounding and supporting structures of the teeth. "MyD88, IRAK2, IRAK4 (MyD88-dependent), and TBK1 (MyD88-independent) were significantly up-regulated in RHG exposed to commensal biofilm compared to gingivitis or cariogenic biofilms." (PMID 31448244, 2019).
Granuloma (1 paper, 2021). A compact, organized collection of mature mononuclear phagocytes, which may be but is not necessarily accompanied by accessory features such as necrosis. "The bacterial colony forming units (CFUs) and granulomas were reduced in rMPT-treated mice; however this difference was not significant in mice lacking TBK1, p47phox, or HK2, compared to the control." (PMID 34068051, 2021).
H1N1 virus infection (1 paper, 2022). "Following H1N1 virus infection, endogenous Co-IP experiment verified that NS2 was associated with IRF7 in the infected cells, with TBK1 as a positive control to interact with IRF7." (PMID 36366509, 2022).
hepatitis C infection (1 paper, 2012). "TANK-binding kinase-1 (TBK1) and IκB kinase ε (IKKε) are essential for IRF-3 phosphorylation, and both kinases were markedly enhanced in B cells with hepatitis C infection." (PMID 22518147, 2012).
Hypercholesterolemia (1 paper, 2022). An increased concentration of cholesterol in the blood. "Together, these data suggest that inhibition of the protein kinases TBK1 and IKKε by amlexanox upregulates bile acid production to increase cholesterol excretion and thus ameliorates hypercholesterolemia." (PMID 35917178, 2022).
hyperlipidemia (1 paper, 2025). "Hyperlipidemia―IRE1α―XBP1―ER stress―STING―TBK1―NF-κB―pro-inflammatory." (PMID 41153813, 2025).
intestinal tumors (1 paper, 2024). "In the case of intestinal tumors, the application of TBK1 inhibitors may need more careful evaluation, especially in the scope of STING agonists." (PMID 39161768, 2024). "However, as inflammation persists, the TBK1-IFN pathway leads to the depletion of immune cells and the creation of an inflammatory microenvironment suitable for tumor growth and distant metastasis colonization, which is particularly evident during the development of intestinal tumors." (PMID 39161768, 2024).
itch (1 paper, 2023). "Spinal down-regulations of TBK1 and IRF3 phosphorylation in these two chronic itch models are elevated by STING activation." (PMID 37122031, 2023).
liver disease (1 paper, 2025). "Collectively, our findings support a model in which TBK1 acts as a metabolic rheostat, integrating inflammatory and nutrient-derived signals to orchestrate mitochondrial quality control and hepatic lipid metabolism, particularly important in the later stages of liver disease." (PMID 41282122, 2025).
liver failure (1 paper, 2022). A liver disease characterized by the liver losing or has lost all of its function. "Germline Tbk1-knockout (Tbk1−/−) mice of a C57BL/6 background die of liver failure, whereas Tbk1−/− mice of 129S5 background (Tbk1Δ/Δ) are viable but highly sensitive to LPS-induced inflammation and display neurodegenerative phenotypes." (PMID 35395857, 2022).
lymphoma (1 paper, 2020). A malignant (clonal) proliferation of B- lymphocytes or T- lymphocytes which involves the lymph nodes, bone marrow and/or extranodal sites. "Survival of cell lines Ly10, Ly03 and Pfeiffer, and of some primary human lymphoma cells, was suppressed by a small molecule IKKε/TBK1 inhibitor, DMX3433." (PMID 32858764, 2020). "Inhibition of IKKε and TBK1 warrants further investigation as a potential therapeutic route to suppress NF‐κB signalling in lymphoma." (PMID 32858764, 2020).
lysosomal storage disease (1 paper, 2024). A metabolic disorder caused by mutations in proteins critical for lysosomal function, including lysosomal enzymes, lysosomal integral membrane proteins, and proteins involved in the post-translational modification and trafficking of lysosomal proteins. "Lysosomes hold potential as an attractive target for therapeutic intervention in ALS, as in addition to VCP, several other ALS associated genes have a role in lysosomal homeostasis (C9orf72, TARDBP, TMEM106B, TBK1, OPTN, SQSTM1) and several lysosomal storage diseases manifest neurological features." (PMID 39593143, 2024).
malaria (1 paper, 2017). Malaria is a serious and sometimes fatal disease caused by a parasite that commonly infects a certain type of mosquito which feeds on humans. "Screening compound libraries for small molecules to block FOSL1 expression in cytoplasm or its interaction with TRAF3/TRIF/TBK1 may lead to therapies that can improve IFN-I response in malaria and other diseases." (PMID 28049150, 2017).
memory impairment (1 paper, 2019). "Patients with Tbk1 mutations exhibit most often the behavioral variant, rather than the language variant of FTD, with early memory impairment being prevalent in most cases." (PMID 31039129, 2019).
mesothelioma (1 paper, 2021). A usually malignant and aggressive neoplasm of the mesothelium which is often associated with exposure to asbestos. "Dotplot of IRF3 and the cGAS/STING signaling pathway genes showed that IRF3 and STING (TMEM173) were expressed in mesothelioma tumor cells, while TBK1 and CGAS expressed mainly in monocyte/macrophages." (PMID 34768716, 2021).
mouth ulcers (1 paper, 2020). "To demonstrate the functional role of IKKε in the macrophage‐mediated transformation, we then used the recently identified inhibitor of IKKε/TBK1, amlexanox, an FDA‐approved drug previously used for the treatment of mouth ulcers." (PMID 31930708, 2020).
MRSA pneumonia (1 paper, 2023). "Therefore, we suggest that the upregulation of Tbk1 and Ikbke genes may be related to upstream initiation of host interferon mechanisms in MRSA pneumonia." (PMID 36830716, 2023).
neuroblastoma (1 paper, 2023). Neuroblastoma (NB) is the most common solid, extracranial childhood tumor. "Moreover, σ1R or TBK1 deficiency also compromised the stress granules’ formation induced by paraquat in mouse neuroblastoma Neuro2a cells." (PMID 37967220, 2023).
neuropathy (1 paper, 2024). A disorder affecting the nervous system that manifests with pain, tingling, numbness, and/or muscle weakness. "As for neuropathy tests, our results showed that intrathecal injection of si-TBK1 could reverse the reduced PWT and PWL, revealing a promoting role of TBK1 in PDN." (PMID 39030571, 2024).
Opportunistic infection (1 paper, 2022). An infection that is caused by a pathogen that would generally not be able to cause an infection in a host with a normal immune system. "Compared to blocking common natural immune targets, such as TBK1 or IFNs, inhibition of cGAS-STING has less risk of immunosuppression and opportunistic infections without keeping the other PRR systems intact." (PMID 36172373, 2022).
optic neuropathies (1 paper, 2021). "Of relevance to a discussion of the role of mitochondria in optic neuropathies, the activity of OPTN as a linker protein is enhanced by being phosphorylated by TANK-Binding Kinase 1 (TBK1), which increases both ubiquitin-OPTN binding affinity and OPTN-LC3 binding affinity." (PMID 34201955, 2021).
periodontal disease (1 paper, 2021). "Current studies produced evidence for using STING-pathway-targeting molecules as part of anticancer therapy, and as vaccine adjuvants against microbial infections; however, the role of the STING/TBK1/IRF3 pathway in periodontal disease pathogenesis is still undiscovered." (PMID 34070809, 2021).
periodontitis (1 paper, 2021). An acute or chronic inflammatory process that affects the tissues that surround and support the teeth. "The literature was searched using the terms “STING”, “STING and periodontitis”, “TBK1”, “TBK 1 and periodontitis”, “IRF3”, “IRF3 and periodontitis”, “cGAS”, and “cGAS and periodontitis” by S.E. and M.Y., using the databases of PubMed/Medline, Scopus, and Web of Science." (PMID 34070809, 2021).
peripheral nerve injury (1 paper, 2024). Injury to a peripheral nerve. "Overall, our data demonstrated that the inhibition of TBK1 could downregulate the level of inflammation in the SDH of PDN mice, inhibiting microglial pyroptosis, alleviating peripheral nerve injury, and finally reducing hyperalgesia." (PMID 39030571, 2024).
polyarthritis (1 paper, 2022). "However, the STING S365A mutant retains the ability to recruit TBK1 and activate NF-κB, and DNase II−/−STING-S365A mice exhibited severe polyarthritis, which was alleviated by neutralizing antibodies against TNF-α or IL-6 receptor." (PMID 34901991, 2022).
preeclampsia (1 paper, 2012). Preeclampsia is a hypertensive disorder of pregnancy that is characterized by new-onset hypertension with proteinuria presenting after 20 weeks of gestation, and depending on mild or severe forms may initially present with severe headache, visual disturbances, and hyperreflexia. "However, there are not articles of PDIA3, TBK1 or LYN related with preeclampsia." (PMID 22873350, 2012).
Primary lateral sclerosis (1 paper, 2026). "We report a 58-year-old woman with a novel splice-site variant in the TANK-binding kinase 1 (TBK1:c.993-2A>C p.Ala332TyrfsTer39) who sequentially developed primary lateral sclerosis (PLS) followed by right temporal variant frontotemporal dementia (rtvFTD)." (PMID 41645024, 2026).
progressive supranuclear palsy (1 paper, 2019). A rare late-onset neurodegenerative disease characterized by supranuclear gaze palsy, postural instability, progressive rigidity, and mild dementia. "More recently, TBK1 mutations have been found in patients with progressive supranuclear palsy and progressive cerebellar ataxia syndromes, expanding the phenotypic spectrum of TBK1-associated disease." (PMID 31160356, 2019).
retinal diseases (1 paper, 2016). "The dysfunction of optineurin and TBK1 in retinal cells is assumed to play a significant role in glaucomatous and other retinal diseases by affecting the autophagy process and survival." (PMID 27454487, 2016).
retinal ischemia (1 paper, 2017). A ischemic disease that involves the retina. "Retinal ischemia damage increased RGCs' senescence in frozen retinal sections and the number of senescent cells in retinal flats; by contrast, the inhibition of TBK1 reduced the retinal ischemic damage." (PMID 28425986, 2017). "We found that acute IOP elevation-induced retinal ischemia directly increases TBK1 expression, triggering Akt S473 phosphorylation, activating Bmi1 phosphorylation, and upregulating the expression of p16, which leads to RGC senescence in cell culture and an IOP-induced retinal ischemia mouse model." (PMID 28425986, 2017). "In the current study, we observed that the expression of TBK1 and RGC senescence peaked at 48 h after acute elevated IOP-induced retinal ischemia." (PMID 28425986, 2017). "Additionally, we examined the expression of TBK1 and p16 following IOP elevation-induced retinal ischemia." (PMID 28425986, 2017).
Rett syndrome (1 paper, 2024). A severe neurodevelopmental disorder affecting the central nervous system. "TBK1, which is rapidly activated in response to mitochondrial damage and is involved in autophagizing damaged mitochondria, is upregulated in Rett syndrome, suggesting abnormalities in mitochondrial function." (PMID 39457485, 2024).
schizophrenia (1 paper, 2022). A major psychotic disorder characterized by abnormalities in the perception or expression of reality. "The UBQLN2 P500S and the TBK1 R271W/GRN T220I carriers have a family history of schizophrenia." (PMID 35964197, 2022). "The relevance between the UBQLN2, TBK1, and schizophrenia is unknown." (PMID 35964197, 2022).
thyroid (1 paper, 2023). "The data suggested that TBK1 exerts a vital function in the promotion of thyroid tumorigenesis." (PMID 36988258, 2023).
thyroid tumor (1 paper, 2023). A benign or malignant neoplasm affecting the thyroid gland. "We first analyzed TBK1 expression in thyroid tumors and normal control tissues." (PMID 36988258, 2023).
toxoplasmosis (1 paper, 2024). A parasitic disease contracted by the ingestion or fetal transmission of toxoplasma gondii. "T. gondii effector GRA4 suppresses host harmful IFN‐I via degrading TBK1 through selective autophagy, which renders this parasitic protein a candidate to develop therapies against toxoplasmosis." (PMID 39031880, 2024). "Therefore, investigating the relationship between T. gondii effectors and TBK1 would be beneficial in explaining why IFN‐I production is often limited compared to IFN‐γ during toxoplasmosis, and for further modification of T. gondii for IFN‐I‐based anti‐tumor therapy." (PMID 39031880, 2024). "This pathway plays an important role in antiviral and antitumor immunity, however the role of TBK1 and its regulatory mechanisms has not yet been explored in toxoplasmosis." (PMID 39031880, 2024). "TBK1 is the core kinase in the signaling pathways of cGAS/RLR and TLRs, which is stringently controlled by various PTMs in infectious diseases and cancer, but its role in toxoplasmosis is not well understood." (PMID 39031880, 2024).
Urea (1 paper, 2025). "Notably, IFNAR1, TBK1, and TRAF6-downstream components of cGAS-STING signaling -were significantly upregulated in the Urea + OGD group, suggesting engagement of DNA damage-driven inflammatory mechanisms." (PMID 41286951, 2025).
uterine corpus endometrial carcinoma (1 paper, 2025). A endometrial carcinoma (disease) that involves the body of uterus. "Kaplan-Meier plotter analysis revealed that low TBK1 expression was associated with a good prognosis in patients with uterine corpus endometrial carcinoma (UCEC)." (PMID 39744441, 2025). "Moreover, we conducted bioinformatic analyses of TBK1, including genetic alteration, survival, DNA methylation, copy number variation, and somatic cell mutation analyses, in patients with uterine corpus endometrial carcinoma (UCEC)." (PMID 39744441, 2025).
viral hepatitis (1 paper, 2024). An acute or chronic inflammation of the liver parenchyma caused by viruses. "Notably, the search results in the PPI network of key target protein of the intersection targets showed that TLR3, TBK1, IRF3, IL6, were important targets associated with viral hepatitis." (PMID 38322849, 2024). "Besides, TLR3, TBK1, IRF3, IL6, were important targets associated with viral hepatitis." (PMID 38322849, 2024).